HMGA2 (high mobility group AT-hook 2)
Diseases named in the same sentence as HMGA2 in open-access papers (continued):
Sharing a sentence is not in itself a finding about the gene and the disease.
melanoma (continued). "HMGA2 is a member of the high-mobility group of AT-hook proteins, which are expressed during embryonic development as well as in different tumors (e.g. squamous cell carcinoma and malignant melanoma)." (PMID 31888467, 2019). "HMGA2 played key roles in melanoma progression and prognosis." (PMID 26796627, 2016). "It has demonstrated that FAK is regulated by HMGA2 in melanoma cells." (PMID 26893968, 2016). "The transfection of let-7b mimic decreased HMGA2 protein expression in melanoma cells." (PMID 26754091, 2016). "To assess whether there is an association between the levels of HMGA2, Twist1 or ZEB1 and miR-33b in melanoma, we analyzed their levels in 72 melanoma patient samples." (PMID 25868853, 2015). "HMGA2 or Twist1 overexpression reverted cordycepin-mediated reduction of melanoma motility." (PMID 25868853, 2015). "To determine whether changes of these gene expressions were dependent on the activities of HMGA2 and Twist1, we transfected melanoma cells with mock, HMGA2 or Twist1 constructs." (PMID 25868853, 2015). "Although the role of HMGA2 in melanoma invasiveness is unknown, TGF-β/GLI2 and MITF inversely regulate invasion and pigmentation in melanoma cells, which is consistent with the present results." (PMID 24733089, 2014). "We examined whether let-7b down-regulates HMGA2 expression in melanoma cells." (PMID 26754091, 2016). "Therefore, we asked whether cordycepin can inhibit melanoma migration by targeting miR-33b and downregulating HMGA2 and Twist1 expression." (PMID 25868853, 2015). "For instance, in melanoma, IGF2BP3 promotes migration and invasion through direct regulation of HMGA2 transcripts." (PMID 37760460, 2023). "Future studies are necessary to determine the effector cell-type that requires the function of Hmga2, pathways modulated by this protein, how it becomes activated in response to UVB, and its relevance to human melanoma." (PMID 29762513, 2018). "Hmga2 is a chromatin-remodeling protein and plays a role as an inducer of epithelial-mesenchymal transition (EMT) in melanoma." (PMID 29762513, 2018). "To this end, we explored publicly available expression data of primary melanoma and extracranial metastases (GSE46517, GSE7553, GSE8401) for levels of HMGA2." (PMID 28852061, 2017). "Since we observed a clear down-regulation of HMGA2 in CD271 knock-down cells, we asked for genes involved in melanoma migration and metastasis supposedly driven by a CD271/HMGA2 axis." (PMID 28852061, 2017). "The cordycepin treatment downregulated the expression of ZEB1, HMGA2 and TWIST1 by more than 50% but had minimal effects on ADAM9, RAC1, SALL4, CTNNB1, ZEB2 and YES1 in these two melanoma cell lines." (PMID 25868853, 2015). "For melanoma samples without TERT promoter mutation, we predicted HMGA2, HIF1, RUNX2 and TAL1 as the most significant regulators." (PMID 31888467, 2019). "Live cell-imaging based scratch-wound assays of melanoma cells with stable knock-down of CD271 revealed a significantly reduced cell migration (3.9fold, p = 1.2E-04) and a reduced expression of FGF13, CSPG4, HMGA2 and AKT3 major candidate regulatory genes of melanoma cell migration." (PMID 28852061, 2017). "Since FGF13, CSPG4 and HMGA2 were not among the top up-regulated genes in the CD271high subset of brain metastases, these factors may not be involved in melanoma brain metastasis." (PMID 28852061, 2017). "Although it was reported that other transcriptional regulator, like HMGA2, can stimulate EMT, ZEB1 may function as the predominant trigger for EMT in melanoma cells, as overexpression of ZEB1 in melanoma cell was sufficient to revert cordycepin-mediated inhibition of EMT." (PMID 25868853, 2015). "The negative correlations between miR-33b levels and HMGA2, Twist1 or ZEB1 expression were detected in 72 patient melanoma tissue samples." (PMID 25868853, 2015).
melanoma (continued). "Using linear regression analysis, miR-33b displayed a significant negative correlation with the expressions of HMGA2, Twist1 and ZEB1, consistent with these genes being regulated by miR-33b in melanoma." (PMID 25868853, 2015).
non-small cell lung carcinoma (24 papers, 2008 to 2025). A group of at least three distinct histological types of lung cancer, including non-small cell squamous cell carcinoma, adenocarcinoma, and large cell carcinoma. "In non-small cell lung cancer, miR-150-5p exerted anti-cancer effects by targeting HMGA2 and Wnt/β-catenin signaling." (PMID 38654006, 2024). "miR-498 has been proposed to target the 3′-UTR of HMGA2 and inhibits its translation in non-small cell lung cancer." (PMID 35031054, 2022). "HMGA1 and HMGA2 are overexpressed in pancreatic adenocarcinomas and non-small cell lung carcinomas (NSCLC), in both squamous and adenocarcinoma histotypes." (PMID 31614829, 2019). "It has been reported that miR-26a is able to inhibit the expression of HMGA2 in gallbladder cancer and non-small cell lung cancer, and upregulate PTEN expression in gastric cancer." (PMID 28522832, 2017). "HMGA1 and HMGA2 proteins were overexpressed in non-small cell lung carcinomas (NSCLC), in both squamous and adenocarcinoma histotypes, in comparison with normal lung and benign tissues." (PMID 25859543, 2015). "miR-26a could regulate the resistance of human non-small cell lung cancer to cisplatin by regulating the expression of HMGA2 through the E2F1-Akt pathway." (PMID 34856955, 2021). "HMGA2 is found on chromosome 12q13-15, and indeed clinically relevant chromosome 12 abnormalities have been reported among the frequent chromosomal abnormalities described in non-small cell lung cancer." (PMID 19025616, 2008). "Notably, HMGA2 expression was found to be associated with response to bintrafusp alfa only in the TNBC cohort, and not in any other expansion cohorts in NCT02517398, including biliary tract cancer, non-small cell lung cancer, and squamous cell carcinoma of the head and neck." (PMID 36568239, 2022). "In male non-small cell lung cancer cells, linc-SPRY3-2/3/4 has been found to interact with IGF2BP3, resulting in a decrease in the stability of specific IGF2BP3 binding mRNAs like anti-apoptotic HMGA2 mRNA and oncogenic c-MYC mRNA." (PMID 38760723, 2024). "Furthermore, miR-498 has been proposed to target the 3′-untranslated region (UTR) of high mobility group AT-hook 2 (HMGA2) and inhibits its translation in non-small cell lung cancer." (PMID 35031054, 2022). "Then the relative gene and protein expressions of let-7f and its target genes, including HMGA2, ARID3B, SMARCAD1, and FZD3, were measured in lung tissues of Non-Small Cell Lung Cancer (NSCLC) patients and A549 cell line using quantitative real-time PCR and Western blotting." (PMID 35488374, 2022). "In non-small cell lung cancer, lncRNA linc-SPRY3 could bind to IGF2BP3 (Insulin Like Growth Factor 2 MRNA Binding Protein 3), which leads to the destabilization of c-Myc and HMGA2, and improves the radiosensitivity of tumors." (PMID 35600868, 2022).
liver cancer (22 papers, 2016 to 2025). An epithelial or non-epithelial malignant neoplasm that arises from the liver. "HMGA2, a protein involved in the transcriptional regulation of liver cancer‐related genes, belongs to the high‐mobility group A2 family." (PMID 40530890, 2025). "To investigate the influence of HMGA2 on the progression of liver cancer, we suppressed HMGA2 expression in liver cancer cells by transfecting them with si-HMGA2." (PMID 39591457, 2024). "Further studies revealed that transfecting liver cancer cells with HMGA2 siRNA in vitro silenced the expression of HMGA2." (PMID 39591457, 2024). "Among these, an enhancer within the human HMGA2 gene’s third intron mediates TET1-promoted cell growth in human liver cancer." (PMID 39335310, 2024). "Downregulated CRNDE attenuates drug resistance of liver cancer cells through enhancing miRNA-33a expression and reducing HMGA2 expression." (PMID 37194105, 2023). "For instance, HMGA2 has been found to promote the expression of EMT marker SNAIL via CREB in liver cancer." (PMID 37553583, 2023). "The pan-deacetylase inhibitor panobinostat, for example, affects liver cancer cell lines by inducing the let-7b-mediated downregulation of HMGA2." (PMID 31979076, 2020). "When miR‐9 and HMGA2 were overexpressed at the same time, the inhibition effect of miR‐9 on the migration and invasion of liver cancer cells disappeared, and the migration and invasion behavior of the cells was aggravated." (PMID 31408273, 2019). "In contrast, liver cancer cells transfected with miR‐9 mimics plus HMGA2 exhibited an increase in migration capacity." (PMID 31408273, 2019). "To assess the impact of miR‐9 on cell growth, we transfected liver cancer cells with miR‐NC, miR‐9 mimics, HMGA2 or miR‐9 mimics plus HMGA2." (PMID 31408273, 2019). "Meanwhile, liver cancer cells transfected with NC‐inhibitor, miR‐9 inhibitor, HMGA2 siRNA or miR‐9 inhibitor plus HMGA2 siRNA." (PMID 31408273, 2019). "Many studies have reported the elevated levels of the HMGA2 protein in cancer tissues and correlated its expression levels with clinicopathological features in various types of cancer, including bladder, breast, colon, lung, ovarian, and liver cancers." (PMID 40204943, 2025). "Additionally, scratch and Transwell assays indicated that silencing HMGA2 in liver cancer cells significantly suppressed both horizontal and vertical migration abilities." (PMID 39591457, 2024). "The CCK-8 assay demonstrated that low levels of HMGA2 could inhibit the proliferation of liver cancer cells." (PMID 39591457, 2024). "HMGA2 exhibited elevated expression across all liver cancer cell lines." (PMID 39591457, 2024). "This highlights the role of HMGA2 in enhancing the migration capabilities of liver cancer cells." (PMID 39591457, 2024). "Some literature suggested that HMGA2 might be the target of miRNA-107, and miRNA-107 could inhibit the proliferation of liver cancer cells by targeting HMGA2 mRNA 3′-UTR." (PMID 34856955, 2021). "For example, BANCR can be used as a potential therapeutic target for liver neoplasms, NEAT1 is necessary for liver neoplasm marker CD44 expression, and LINC00473 promotes the progression of liver cancer by acting as microRNA-195 ceRNA and increasing HMGA2 expression." (PMID 35058974, 2021). "The high mRNA expression of pescadillo (PES1), high mobility group A2 (HMGA2), microtubule-associated serine and threonine kinase 2 (MAST2), trophinin-associated protein (TROAP), and MEX3A was associated with poor prognosis for liver cancer." (PMID 32420386, 2020). "Functionally, HMGA2-sh-3p20-enhanced HMGA2 accelerates the growth of liver cancer cells." (PMID 28522832, 2017). "Therefore, it seems plausible that downregulation of hsa-let-7b leads to increased levels of HMGA2, which further contributes to the generation of liver cancer." (PMID 27677077, 2016).
liver cancer (continued). "Notably, downregulation of CRNDE could suppress drug resistance of liver cancer cells by increasing microRNA-33a expression and decreasing HMGA2 expression." (PMID 34454479, 2021). "Though the association between hsa-let-7b, HMGA2 and CC development has not been reported previously, we hypothesize that guessed the functional mechanism might be similar to that in liver cancer." (PMID 27677077, 2016). "It has been indicated that HULC accelerated liver cancer by inhibiting PTEN via autophagy cooperation to miR15a and increasing HMGA2 expression via sequestration of the miR186." (PMID 32010942, 2020). "HDACIs such as panobinostat can inhibit Hmga2 gene expression in NIH3T3, F9, Hela, liver cancer cell lines and human cord blood-derived multipotent stem cells." (PMID 28415789, 2017). "The stable/up-regulated expression of hsa-let7b-5p after treatment could be inversely correlated with the down-regulation of HMGA2, a non-transcription factor with well-known oncogenic properties as previously shown in liver cancer cell lines." (PMID 29762469, 2018).
thyroid cancer (22 papers, 2003 to 2025). "Molecules like PAPPA, TIMP1, and HMGA2 are particularly noteworthy due to their substantial sample sizes and diagnostic utility, making them promising candidates for enhancing thyroid cancer diagnosis." (PMID 40346322, 2025). "We identified several targets of this miRNA closely associated with EMT, among which HMGA2, a well-described molecular marker able to distinguish between benign and malignant thyroid tumors, may be an essential contributor to tumor invasion." (PMID 37445942, 2023). "Taken together, our data support that HMGA2 may serve as both a potential diagnostic marker and therapeutic target in TC and suggest that HMGA2 inhibition offers promising perspectives for thyroid cancer treatment." (PMID 37445942, 2023). "In thyroid cancer, HMGA2 is overexpressed and is already a well-described molecular marker able to distinguish between benign and malignant thyroid tumors." (PMID 40004107, 2025). "To conclude, the characterisation of HMGA2 in thyroid tumorigenesis suggests its potential involvement in cell dedifferentiation and tumor progression of thyroid cancers." (PMID 40004107, 2025). "This study aimed to further analyze the role of HMGA2 in PTC tumorigenesis by exploring the expression of thyroid-specific and EMT-related genes following HMGA2 knockdown in thyroid cancer cell lines." (PMID 40004107, 2025). "To address this, we first knocked down HMGA2 in two thyroid cancer derived cell lines: TPC-1 cells, derived from a RET/PTC1 positive PTC, and BCPAP cells, originating from a BRAFV600E positive poorly differentiated PTC." (PMID 40004107, 2025). "This study aimed to improve our understanding of the role of HMGA2 in PTC tumorigenesis by exploring the expression of thyroid-specific and EMT-related genes following HMGA2 knockdown in two thyroid cancer cell lines: TPC-1 and BCPAP cells." (PMID 40004107, 2025). "The use of mouse models of thyroid cancer allows to confirm and to further investigate the role of HMGA2 in cell invasion and the relationship between HMGA2 and thyroid differentiation." (PMID 40004107, 2025). "Assessment of the functional role of HMGA2 after knocking down HMGA2 using a siRNA revealed that the capacity of invasion of thyroid cancer cells was significantly reduced, which was also observed when the MAPK pathway was inhibited." (PMID 37445942, 2023). "To address the functional role of HMGA2, we first analyzed its expression in different thyroid cancer cell lines (TPC-1, BCPAP and K1)." (PMID 37445942, 2023). "Because therapeutic strategies based on miRNA delivery are still challenging and HMGA2 is generally not or barely expressed in adult tissues while re-expressed in thyroid cancer, HMGA2 inhibition has therapeutic potential in thyroid cancer." (PMID 37445942, 2023). "The use of in vivo mouse models of thyroid cancer will enable us to confirm and further investigate the role of miR-204-5p and HMGA2 in cell invasion." (PMID 37445942, 2023). "lncRNA HIT000218960 was reported to promote thyroid cancer progress by upregulating the neighboring protein-coding gene HMGA2." (PMID 29581707, 2018). "Many studies have confirmed that HMGA2 is important in tumorigenesis and tumor progression, including thyroid cancer." (PMID 27793213, 2016). "The telomere-protective role of HMGA2 was confirmed in a human thyroid cancer cell model devoid of endogenous HMGA2 where the introduction of exogenous HMGA2 increased telomere stability." (PMID 26799419, 2016). "In thyroid cancer, elevated levels of HMGA2 are considered a molecular marker to distinguish benign and malignant thyroid neoplasms." (PMID 24723911, 2014). "A good example is that of HMGA2, which is undetectable in most differentiated tissues, but highly expressed in various cancers, including neuroblastoma and pancreatic, lung, and thyroid cancers 68–71." (PMID 20179807, 2010).
thyroid cancer (continued). "This was demonstrated by comparing the frequency of radiation or papilloma virus E7 gene-induced thyroid carcinomas in mice carrying disrupted HMGA2 (pygmy mice) and that in mice carrying wild-type HMGA2." (PMID 14647145, 2003). "So, HMGA2 may be a new molecular target for thyroid cancer, and our data suggest suramin as a potential new therapeutic approach." (PMID 40004107, 2025). "In our previous study describing the role of miR-204-5p and HMGA2 in PTC, we proposed that inhibiting HMGA2 could offer promising perspectives for thyroid cancer treatment." (PMID 40004107, 2025). "Finally, we showed that HMGA2 inhibition by suramin reduced cell invasion and induced differentiation expression in vitro, indicating a new therapeutic strategy for treating thyroid cancer." (PMID 40004107, 2025). "However, further in vitro and in vivo studies are necessary to evaluate the potential relationship between HMGA2 and the TGFβ signalling pathway in thyroid cancer." (PMID 37445942, 2023). "Our data suggest that HMGA2 inhibition offers promising perspectives for thyroid cancer treatment." (PMID 37445942, 2023). "Targeting HMGA2 could therefore represent a promising therapeutic strategy for treating thyroid cancer." (PMID 37445942, 2023). "On the contrary, we did not observe any effects on the growth, proliferation, or apoptosis of thyroid cancer cells after knocking down HMGA2, whereas, as expected, we observed a significant decrease in the proliferation rate of these cells when the MAPK signalling pathway was inhibited." (PMID 37445942, 2023). "PTC has a higher level of HMGA2 mRNA, and HMGA2 expression in thyroid nodules could be a marker for thyroid cancer preoperative diagnosis." (PMID 35213273, 2022). "Previous reports indicated that let-7f targets HMGA2 in thyroid cancer." (PMID 34150620, 2021). "Binding of HMGA2 to these DNA conformations protected stalled replication forks from endonuclease digestion and conferred a survival advantage onto HMGA2+ cancer cells, including thyroid cancer cells, when exposed to chemotherapeutics such as hydroxyurea used in the treatment of cancer patients." (PMID 24723911, 2014). "Moreover, it has been shown that in thyroid carcinomas the increased expression of HMGA2 and PLAG1 is detectable on the mRNA as well as on the protein level." (PMID 24516594, 2014). "Hence, HMGA2 may be a new molecular target for thyroid cancer, and our data suggest suramin as a potential new therapeutic approach." (PMID 40004107, 2025). "This study aimed to elucidate more deeply the role of HMGA2 in PTC progression by investigating its potential involvement in dedifferentiation and EMT, both critical processes driving tumor aggressiveness and thyroid cancer progression." (PMID 40004107, 2025). "Therefore, one hypothesis would be that HMGA2 could induce the TGFβ pathway resulting in increasing the EMT program in thyroid cancer cells where TGFβ could, in turn, contribute to the progression of tumorigenesis through secretion of growth factors and cytokines in the stroma." (PMID 37445942, 2023). "Deacetylase inhibitors reduced cell viability, restored NIS and H19, and suppressed the oncogenes HMGA2 and TTF1 in thyroid cancer cells." (PMID 29561759, 2018). "Presence of HMGA1 and/or HMGA2 confers enhanced BER capacity and chemoresistance against alkylating agents onto thyroid cancer cells." (PMID 24723911, 2014). "Herein, we observed a strong correlation between the expression of HMGA2 and PLAG1 in 14 benign and 23 malignant thyroid tumors." (PMID 24516594, 2014). "However, the interplay between HMGA2, dedifferentiation and EMT, and the TGFβ signaling pathway remains unexplored in the context of thyroid cancer." (PMID 40004107, 2025). "This suggests that miR-204-5p could inhibit the invasion of thyroid cancer cells by targeting downstream transcripts of the MAPK signalling pathway specifically regulating invasion, including HMGA2." (PMID 37445942, 2023).